ACY1 (aminoacylase 1)
Diseases named in the same sentence as ACY1 in open-access papers:
ACY1 is named in the same sentence as 74 diseases in open-access papers, as found by Europe PMC text mining. Sharing a sentence is not in itself a finding about the gene and the disease. The quoted sentences say what the papers report.
colorectal cancer (5 papers, 2021 to 2024). A primary or metastatic malignant neoplasm that affects the colon or rectum. "However, a recent study reported that the overexpression of ACY1 is associated with colorectal cancer progression." (PMID 35059422, 2021). "Literature data demonstrated that ACY1 knockdown in colorectal cancer cells inhibits proliferation and increases apoptosis, becoming an interesting target to explore." (PMID 34320944, 2021). "ACY1 is also a target of miR-212-5p and has been reported to increase the proliferation of colorectal cancer HT-29 cells." (PMID 33760887, 2021).
Cirrhosis (4 papers, 2019 to 2022). A chronic disorder of the liver in which liver tissue becomes scarred and is partially replaced by regenerative nodules and fibrotic tissue resulting in loss of liver function. "Autoantibodies recognized aminoacylase-1 (ACY1) were considered biomarkers to differentiate HBV-related cirrhosis and CHB patients by serum proteomic detection." (PMID 36118247, 2022). "ACY1 autoantibodies were considered as biomarkers to differentiate HBV-related cirrhosis and CHB patients." (PMID 36118247, 2022). "Autoantibodies against aminoacylase-1 (ACY1) (an enzyme that participates in the urea cycle and the metabolism of amino groups) was identified as a marker of cirrhosis in patients with chronic hepatitis B (CHB)." (PMID 31726658, 2019).
neuroblastoma (3 papers, 2021 to 2023). Neuroblastoma (NB) is the most common solid, extracranial childhood tumor. "Aminoacylase 1 (ACY1) has been implicated as a putative tumor suppressor in a variety of carcinomas, including small-cell lung cancer, renal clear cell carcinoma, hepatocellular carcinoma, and neuroblastoma." (PMID 37271807, 2023). "Some studies also discovered that ACY1 acted as a tumor suppressor for renal cell carcinoma, neuroblastoma and HCC." (PMID 35059422, 2021).
Obesity (3 papers, 2024 to 2025). Accumulation of substantial excess body fat. "Higher levels of the protein F7 (coagulation factor VII) have been linked to cardiovascular disease and obesity, while previous research indicates that proteins ACY1 (aminocyclase 1) and GSTA1 (glutathione S-transferase alpha 1) are positively associated with T2D." (PMID 38337712, 2024). "Additionally, NAC suppressed the expression of key obesity-related proteins, including fatty acid binding protein 4 (FABP4), monoamine oxidase A (MAOA), heat shock protein 70 (HSP70), aminoacylase-1 (ACY-1), and transketolase (TKT) in 3T3-L1 cells." (PMID 41149623, 2025).
renal cell carcinoma (3 papers, 2020 to 2022). "ACY1 expression was significantly reduced in small cell lung and renal cell carcinomas, suggesting that it acted to inhibit tumorigenesis." (PMID 36428796, 2022). "In small cell lung cancer (SCLC), liver cancer, and renal cell carcinoma, ACY1 expression has been significantly reduced, suggesting that ACY1, in these tumors, acts as tumor suppressor." (PMID 32650388, 2020).
small cell lung carcinoma (3 papers, 2021 to 2024). Small cell lung cancer (SCLC) is a highly aggressive malignant neoplasm, accounting for 10-15% of lung cancer cases, characterized byrapid growth, and early metastasis. "Acy1 is a cytosolic enzyme that catalyzes the hydrolysis of acylated L-amino acids to L-amino acids and acyl group, and its activity has been shown to decrease in small cell lung cancer cell lines and tumors." (PMID 38730628, 2024). "In contrast, ACY1 is a putative tumor suppressor in small cell lung cancer and hepatocarcinoma." (PMID 34320944, 2021).
colon cancer (2 papers, 2022 to 2024). "Unfortunately, no data on the correlation between radiotherapy and ACY1 expression in colon cancer patients were available in TCGA and GEO datasets." (PMID 36428796, 2022). "However, there was no information on the correlation between radiotherapy and ACY1 expression levels in patients with colon cancer in TCGA and GEO datasets." (PMID 36428796, 2022).
liver cancer (2 papers, 2020 to 2022). An epithelial or non-epithelial malignant neoplasm that arises from the liver. "Conversely, however, ACY1 was overexpressed in liver cancer, and ACY1 levels were associated with tumor proliferation, invasion, and metastasis." (PMID 36428796, 2022).
type 2 diabetes (2 papers, 2022 to 2024). "The three studies used for the diabetes comparison represent the largest candidate protein characterisations of type 2 diabetes to date and the top markers identified included aminoacylase-1 (ACY-1), sex hormone-binding globulin (SHBG) and growth hormone receptor (GHR)." (PMID 35023833, 2022).
atherosclerosis (1 paper, 2014). A disease characterized by the build-up of fatty material and calcium deposition in the arterial wall resulting in partial or complete occlusion of the arterial lumen. "Deficiency in aminoacylase 1, which converts NAM to methionine, has been associated with human diseases and increased L-carnitine, which can be converted to trimethylamine-N-oxide (TMAO), has been linked to atherosclerosis in mice." (PMID 24475228, 2014).
autism (1 paper, 2023). Persistent deficits in social interaction and communication and interaction as well as a markedly restricted repertoire of activity and interest as well as repetitive patterns of behavior. "To date, patients with ACY1 deficiency have various clinical presentations but most present with neurological symptoms, such as mental retardation, bradykinesia, muscle hypotonia, language developmental disorders, growth retardation, and autism behavior." (PMID 37378314, 2023).
brain malformations (1 paper, 2022). "The clinical manifestation of ACY1 deficiency is heterogeneous and includes muscular hypotonia, brain malformations, ID and other neurologic symptoms, while normal psychomotor development has also been noted in some individuals." (PMID 35627165, 2022).
cervical cancer (1 paper, 2022). A primary or metastatic malignant neoplasm involving the cervix. "Data on cervical cancer in TCGA showed worse overall survival (p = 0.076), DSS (p = 0.037), and PFI following radiotherapy (p = 0.046) in patients with high ACY1 expression." (PMID 36428796, 2022).
cognitive decline (1 paper, 2019). "In analyses of longitudinal data, we showed that baseline levels of ACY1 and GHR—and, to a lesser extent, OMD—associated with subsequent rates of cognitive decline in our Discovery Cohort, with baseline GHR predicting subsequent cognitive course in the Replication Cohort as well." (PMID 31603904, 2019). "Fourth, we note that baseline levels of GHR, ACY1, and, to a lesser extent, OMD predicted future cognitive decline in individuals with PD from the Discovery Cohort." (PMID 31603904, 2019). "In particular, we have identified four plasma proteins—BSP, OMD, ACY1, and GHR—with consistent alterations in PD, one of which (GHR) also predicted subsequent cognitive decline in multiple cohorts, across multiple cognitive testing instruments." (PMID 31603904, 2019).
colon adenocarcinoma (1 paper, 2022). "Similarly, ACY1 levels were significantly higher in colon adenocarcinoma (COAD) and rectum adenocarcinoma (READ) tissues than in adjacent noncancerous samples, suggesting a general tumor-activator role of ACY1." (PMID 36428796, 2022).
developmental delays (1 paper, 2025). "ACY1 is an enzyme that plays a key role in protein breakdown and amino acid salvage, and its deficiency has been linked to metabolic imbalance and developmental delays." (PMID 41071435, 2025).
infantile spasms (1 paper, 2023). A rare epilepsy syndrome characterized by onset of epileptic spasms in infants between 2 and 12 months of age, and rarely up to 24 months. "For example, ACY1, known to cause a rare inborn error of metabolism, was reported in two patients from the same family who presented with infantile spasms and severe developmental and intellectual delay." (PMID 37628333, 2023).
Insulin resistance (1 paper, 2023). Increased resistance towards insulin, that is, diminished effectiveness of insulin in reducing blood glucose levels. "Free amino acid levels generated by overexpression of ACY1 play a role in insulin secretion and glucose homeostasis and could eventually lead to T2D with impaired ß-cell function and insulin resistance." (PMID 36777185, 2023).
kidney injury (1 paper, 2022). Trauma to the kidney. "We found that mice lacking ACY1 have a trend for elevated blood levels of N-acetylserine and that this biochemical impairment is markedly worsened with the onset of kidney injury." (PMID 36048534, 2022).
leukemia (1 paper, 2024). A malignant (clonal) hematologic disorder, involving hematopoietic stem cells and characterized by the presence of primitive or atypical myeloid or lymphoid cells in the bone marrow and the blood. "We first analysed the DA1-3b leukemia model and among the 70 commonly mutated genes in dormant leukemia DA1-3b/D365 and parental DA1-3b cells, ten genes (Ttc7b, Dnmt3b, Ap1b1, Ne1, Nedd4, Acy1, Cyp11a1, Htr2c, Magee1 and Gdi1) were amplified in dormant and parental cells." (PMID 39223638, 2024).
liver cirrhosis (1 paper, 2021). "We found that the level of serum ACY1 autoantibody in HBV-related liver cirrhosis was higher than that observed in CHB in our previous study." (PMID 35059422, 2021).
liver fibrosis (1 paper, 2021). "The diagnostic performance of CENPF and ACY1 autoantibodies for staging liver fibrosis tested by ELISA." (PMID 35059422, 2021). "The relative titers of CENPF and ACY1 autoantibodies in patients with different stages of liver fibrosis were significantly higher than those in healthy controls." (PMID 35059422, 2021). "To confirm the diagnostic performance of autoantibodies for liver fibrosis staging, we selected autoantibodies to CENPF and ACY1 for further examination by ELISA based on the protein microarray results and our previous studies." (PMID 35059422, 2021). "Comparison of the positivity rate of autoantibodies against CENPF, ACY1 and the two autoantibodies combined between different stages of liver fibrosis showed significant differences between S4 and S0-1, S4 and S2-3, S4 and S0-3, S2-4 and S0-1." (PMID 35059422, 2021). "In this study, we found that autoantibody to ACY1 had potential value for determining the stage of HBV-induced liver fibrosis." (PMID 35059422, 2021). "CENPF and ACY1 autoantibodies had AUC values of 0.746 and 0.685, sensitivity of 58.14 and 74.42%, and specificity of 88.41 and 60.87%, respectively, for discriminating liver fibrosis stages S4 and S0-1." (PMID 35059422, 2021). "In the present study, the results of the protein microarray showed that autoantibodies to CENPF, ACY1, ENO1, and HSPA6 may have underlying detection values for liver fibrosis staging." (PMID 35059422, 2021). "CENPF and ACY1 autoantibodies had area under the curve values of 0.746 and 0.685, 58.14 and 74.42% sensitivity, and 88.41 and 60.87% specificity, respectively, for discriminating liver fibrosis stages S4 and S0-1." (PMID 35059422, 2021). "The prevalence of CENPF and ACY1 autoantibodies was not correlated with age, sex or the level of inflammation, suggesting that these autoantibody biomarkers may be independent predictive factors for liver fibrosis." (PMID 35059422, 2021).
lymph node metastasis (1 paper, 2022). "In addition, ACY1 expression levels were lower in patients with KRAS mutation but no lymph node metastasis (group B) than in group C. The expression levels were lowest in patients without lymph node metastasis and KRAS mutation (group A)." (PMID 36428796, 2022).
Menkes disease (1 paper, 2023). A usually severe multisystemic disorder of copper metabolism, characterized by progressive neurodegeneration and marked connective tissue anomalies as well as typical sparse abnormal steely hair.
mild cognitive impairment (1 paper, 2025). "For example, a Pennsylvania cohort identified four serum proteins—bone sialoprotein (BSP), osteomodulin (OMD), aminoacylase-1 (ACY1), and growth hormone receptor (GHR)—as PD biomarkers, yet these were not specific to PD when compared to ALS or mild cognitive impairment." (PMID 40699858, 2025).
non-small cell lung carcinoma (1 paper, 2022). A group of at least three distinct histological types of lung cancer, including non-small cell squamous cell carcinoma, adenocarcinoma, and large cell carcinoma. "In addition, ACY1 promoted the progression of non-small cell lung cancer by activating phosphoinositide 3-kinase/Akt signaling in a phosphatase and tensin homolog-dependent manner." (PMID 36428796, 2022).
prostate carcinoma (1 paper, 2025). A carcinoma that arises from epithelial cells of the prostate gland. "Notably, enzymes governing polyamine biosynthesis, including glutamic oxaloacetic transaminase 2 (GOT2), aminoacylase-1 (ACY1), ODC, and SDS, exhibit overexpression in prostate cancer, while ornithine aminotransferase (OAT) demonstrates insufficient expression." (PMID 41179661, 2025).
rectal cancer (1 paper, 2022). A primary or metastatic malignant neoplasm that affects the rectum. "We also examined the correlation between baseline ACY1 expression levels and tumor response to chemoradiotherapy in patients with rectal cancer." (PMID 36428796, 2022). "ACY1 expression decreased with increasing chemoradiotherapy response in patients with rectal cancer in the GSE46862 dataset." (PMID 36428796, 2022). "We also evaluated the association between the prognosis of radiotherapy and ACY1 expression in patients with rectal cancer and showed that high ACY1 expression was significantly correlated with shorter DSS (p = 0.032)." (PMID 36428796, 2022). "Overall, these results suggested that ACY1 might be involved in the response to radiotherapy in cervical and rectal cancers." (PMID 36428796, 2022).
steatosis (1 paper, 2017). Increased lipid within the cytoplasm of cells. "However, we found increased steatosis associated with aminoacylase 1 levels." (PMID 28266614, 2017).
tumor (12 papers, 2011 to 2025). "Knockdown of aminoacylase 1 in HCC cells is directly linked to an increase in the cell viability, tumor invasiveness the expression of TGF-β1 and ERK1, which proves its tumor-suppressing potential." (PMID 36014345, 2022). "To explore the impact of ACY1 on tumor radiotherapy, we analyzed related research in TCGA and GEO datasets." (PMID 36428796, 2022). "Despite the well-characterized aminoacylase activity of ACY1, experimental evidence regarding its role in tumor biology is controversial." (PMID 36428796, 2022). "Next, we observed upregulation in two tumor-suppressor genes: aminoacylase 1 and RB1." (PMID 36014345, 2022). "However, aminoacylase-1 (encoded by ACY1), which is responsible for the degradation of these N-acetyl amino acids, has been found to be inactivated in several tumor types." (PMID 25091696, 2014). "Among them, aminoacylase-1, pre-mRNA-processing factor 19, T-complex protein 1 subunit α and T-complex protein 1 subunit β (TCP1β) are reported for the first time to be differentially expressed between tumor and normal colon mucosa." (PMID 21973086, 2011). "We explored the potential role of ACY1 in CRC progression by assessing its expression profiles in tumor and adjacent noncancerous tissues in TCGA datasets using the “DiffExp module” of TIMER." (PMID 36428796, 2022). "However, there were no obvious correlations between ACY1 expression and pathologic TNM stage, the presence of colon polyps, or residual tumor for CRC in TCGA datasets." (PMID 36428796, 2022).
cancer (4 papers, 2021 to 2023). A tumor composed of atypical neoplastic, often pleomorphic cells that invade other tissues. "The current results from TCGA and GEO databases verified that high ACY1 expression levels were associated with lymph node metastasis and shorter cancer-specific survival in CRC." (PMID 36428796, 2022). "Several studies have shown the roles of ACY1 in diverse cancers." (PMID 36428796, 2022). "However, both Ccdc117 and ACY1 primarily appear to play a role in cancers, which are a group of diseases that are mechanistically different from vascular disease." (PMID 33760887, 2021).
cardiovascular disease (2 papers, 2024 to 2025). "Within this context, the present work identified ADAMTSL2 and ACY1 as two aptamer-based protein mediators significantly associated with semaglutide-induced MASH resolution that are implicated in cardiovascular disease and fibrosis." (PMID 40691365, 2025). "Thus, ACY1 appears to play an interconnected role in metabolic diseases that are risk factors for cardiovascular disease and MASH." (PMID 40691365, 2025).
infection (2 papers, 2021 to 2024). The state of being infected such as from the introduction of a foreign agent such as serum, vaccine, antigenic substance or organism. "Aminoacylase-1 (ACY-1) has been reported to play a role in resistance to pathogen infection in the model plant Nicotiana benthamiana." (PMID 34367193, 2021).
neurological diseases (2 papers, 2023). "ACY1 deficiency is a neurological disorder caused by mutations in ACY1 and characterized by high levels of acetylated amino acids." (PMID 36777185, 2023). "Thus, considering its expression in neurons and its role in neurological diseases, we chose ACY1 as a potential candidate to perform further study." (PMID 37378314, 2023).
ACY1 also shares sentences with these, for which no sentence is quoted: aminoacylase 1 deficiency (2 papers); Encephalopathy (2); metabolic disease (2); Myocardial fibrosis (2); adenoma (1); adrenocortical carcinoma (1); amyotrophic lateral sclerosis (1); aspartylglucosaminuria (1); bladder urothelial carcinoma (1); brain cancer (1); breast carcinoma (1); breast invasive carcinoma (1); central nervous system disorder (1); cervical squamous cell carcinoma (1); chronic hepatitis (1); chronic hepatitis B (1); colon polyps (1); connective tissue disorder (1); deafness (1); diabetes (1); diffuse large B-cell lymphoma (1); dimethylglycine dehydrogenase deficiency (1); Dystonia (1); endocervical adenocarcinoma (1); hearing loss (1); hepatocellular carcinoma (1); hyperprolinemia type 1 (1); Intellectual disability (1); kidney disease (1); lung adenocarcinoma (1).
A further 10 diseases each share a sentence with ACY1 in 1 paper.